SLC24A1 (solute carrier family 24 member 1)
Description:
Calcium, potassium:sodium antiporter that transports 1 Ca(2+) and 1 K(+) in exchange for 4 Na(+). Critical component of the visual transduction cascade, controlling the calcium concentration of outer segments during light and darkness. Light causes a rapid lowering of cytosolic free calcium in the outer segment of both retinal rod and cone photoreceptors and the light-induced lowering of calcium is caused by extrusion via this protein which plays a key role in the process of light adaptation.
Synonyms: KIAA0702; NCKX1; NCKX; RODX; HsT17412; CSNB1D
Tractability: Antibody: UniProt places it where antibodies can reach, with high confidence; its Gene Ontology location is reachable by antibodies, with high confidence; UniProt predicts a signal peptide or a membrane-spanning region.
Gene: Protein-coding gene on chromosome 15 (65,611,366 to 65,660,995, forward strand). Ensembl gene ENSG00000074621.
Subcellular location: Cell membrane
Pathways (Reactome):
Disease: Defective SLC24A1 causes congenital stationary night blindness 1D (CSNB1D)
Sensory Perception: Activation of the phototransduction cascade
Transport of small molecules: Sodium/Calcium exchangers
Gene Ontology:
Molecular function: calcium, potassium:sodium antiporter activity; protein binding; calcium channel activity
Biological process: calcium ion transmembrane transport; intracellular calcium ion homeostasis; potassium ion transmembrane transport; sodium ion transmembrane transport; calcium ion import across plasma membrane; calcium ion transport; long-term synaptic depression; long-term synaptic potentiation; response to light intensity; visual perception; transmembrane transport
Cellular component: plasma membrane; membrane; neuronal cell body; outer membrane
Genetic constraint (gnomAD): Loss-of-function variants: 44 observed, 73.49 expected, observed/expected ratio (o/e) 0.6, 90% interval 0.47 to 0.77. The upper end of that interval is the gene's LOEUF score, 0.77, which puts it in group 3 of 6, group 1 being the genes least tolerant of losing a copy. Missense variants: 1,113 observed, 1,321.8 expected, observed/expected ratio (o/e) 0.84, 90% interval 0.8 to 0.88. Synonymous variants: 431 observed, 490.3 expected, observed/expected ratio (o/e) 0.88, 90% interval 0.81 to 0.95.
Gene-disease validity (ClinGen):
ClinGen rates the evidence that SLC24A1 causes each of these diseases.
inherited retinal dystrophy (autosomal recessive): Definitive. An instance of retinal degeneration that is caused by an inherited modification of the individual's genome.
Homologues: Orthologues: chimpanzee SLC24A1 (99% identical), macaque SLC24A1 (93% identical), pig SLC24A1 (74% identical), rat Slc24a1 (70% identical), mouse Slc24a1 (69% identical), guinea pig SLC24A1 (60% identical), dog SLC24A1 (58% identical), tropical clawed frog slc24a1 (40% identical), zebrafish slc24a1 (37% identical), Drosophila melanogaster Nckx30C (27% identical), Caenorhabditis elegans ncx-4 (23% identical), Caenorhabditis elegans ncx-5 (22% identical). Paralogues in human: SLC24A2 (34% identical), SLC24A3 (21% identical), SLC24A4 (20% identical), SLC24A5 (16% identical).
Diseases named in the same sentence as SLC24A1 in open-access papers:
SLC24A1 is named in the same sentence as 21 diseases in open-access papers, as found by Europe PMC text mining. Sharing a sentence is not in itself a finding about the gene and the disease. The quoted sentences say what the papers report.
congenital stationary night blindness (7 papers, 2013 to 2025). "The SLC24A1 gene is involved in pigment-related diseases, and its mutational effect plays a role in the development of congenital stationary night blindness." (PMID 38200816, 2023). "Even if very recently, another solute carrier, Slc24a1 has been implicated in congenital stationary night blindness, further experiments will be needed to clearly implicate those transporters in hypoglycemic-induced retinal cell death and diabetic retinopathy." (PMID 26918849, 2016). "A major novel finding from this study was the association of two genes, GNAT1 and SLC24A1, with RP that had previously only been associated with congenital stationary night blindness (CSNB)." (PMID 27624628, 2016). "Mutations in SLC24A1, a gene encoding the photoreceptor-specific sodium/calcium exchanger, have been linked to autosomal recessive congenital stationary night blindness." (PMID 23687432, 2013). "In retinal rods, SLC24A1 is the principal extruder of calcium ions during light adaptation, and recessive mutations have been described in families presenting congenital stationary night blindness (CSNB1D), a non-progressive retinal disorder associated with impaired night vision." (PMID 31170158, 2019).
night blindness (4 papers, 2016 to 2020). Inability to see clearly in dim light. "For example, many genes harboring mutations implicated in retinal degenerations characterized predominantly by night blindness–such as RHO, SLC24A1, and GNAT1–were confirmed to be selectively expressed in rods." (PMID 32555229, 2020).
autosomal recessive congenital stationary night blindness (3 papers, 2011 to 2022). "Mutations in SLC24A1 (NCKX1) cause one of several forms of autosomal-recessive congenital stationary night blindness (CSNB)." (PMID 36614039, 2022). "Mutations in at least one gene from each family have previously been associated with retinal disease: Klhl7 with autosomal dominant RP, Slc24A1 with autosomal-recessive congenital stationary night blindness, and Znf513 with autosomal-recessive retinitis pigmentosa (RP)." (PMID 22162623, 2011).
retinal disease (2 papers, 2011 to 2016). "We report the association of many previously unreported variants with retinal disease, as well as new disease phenotypes associated with known genes, including the first association of the SLC24A1 gene with retinitis pigmentosa." (PMID 27624628, 2016).
asthma (1 paper, 2014). "In SLC24A1, where we had observed an indel frameshift nominally associated with asthma in the Hutterites (p = 0.01, OR = 2.38), we observed 23 rare missense mutations and one nonsense mutation in the Puerto Rican individuals." (PMID 25116239, 2014).
cervical cancer (1 paper, 2026). A primary or metastatic malignant neoplasm involving the cervix. "Eleven driver genes were identified; among SLC24A1 was a driver gene in both the overall samples and subgroups, suggesting it is a key driver gene in cervical cancer." (PMID 42027431, 2026).
mastitis (1 paper, 2022). Inflammation of breast tissue during lactation or postpartum due to an obstructed duct or infection. "SLC24A1 has also been shown to be downregulated in cows with subclinical mastitis, while MEGF11 is associated with somatic cell count in cattle." (PMID 35659541, 2022).
retinal disorder (2 papers, 2019 to 2025). Any disease or disorder of the retina. "SLC24A1 can be associated with even milder RP, but is not shown as fewer than five patients had SLC24A1‐associated retinopathy." (PMID 40013354, 2025).
tumor (2 papers, 2021 to 2024). "The genes that appeared most frequently among the top projected targets for the 15 patient tumor samples were SLC24A1, ARTN, DHRSX, TEX261, and FRMD8." (PMID 34662337, 2021).
SLC24A1 also shares sentences with these, for which no sentence is quoted: cataract (2 papers); retinal degeneration (2); retinitis pigmentosa (2); autosomal recessive retinitis pigmentosa (1); cerebral ischemia (1); cognitive decline (1); diabetic retinopathy (1); epilepsy (1); macular degeneration (1); Macular dystrophy (1); Pigmentary retinopathy (1); Stargardt disease (1).